TERT (telomerase reverse transcriptase)
Diseases named in the same sentence as TERT in open-access papers (continued):
Sharing a sentence is not in itself a finding about the gene and the disease.
cancer (continued). "It has been well established that the aberrant TERT expression confers cancer cells not only unlimited proliferative potential by stabilizing telomere sizes, but also aggressive phenotypes via its telomere lengthening-independent mechanisms." (PMID 26934125, 2016). "In cancer cells TERT is transcriptionally reactivated by the oncogenic transcription factors Myc, nuclear factor NF-κB, and β-catenin." (PMID 27556185, 2016). "Cancer-related TERT expression and telomerase activation is a specific biomarker for malignancies, and efforts have long been made to set up TERT or telomerase detection approaches for cancer diagnosis." (PMID 27438857, 2016). "Activated TERT transcription in many cancers leads to increased telomerase activity to counteract telomere shortening and promotes malignant transformation of normal cells." (PMID 26716642, 2016). "HBV integration also leads to elevated expression of several other cancer-related genes, including TERT, MLL4 and CCNE1." (PMID 26769853, 2016). "As we all know, TERT has a pleiotropic role in sustained proliferation and survival potentials of various cancer cells." (PMID 26725521, 2016). "On the other hand, the observed low level of TERT promoter methylation in normal thyroids is in agreement with reports of several different types of non-cancer cells." (PMID 26870890, 2016). "In this study, we also found that the expression of TERT was higher in the NPC tissues compared to the non-cancer nasopharyngeal tissues." (PMID 26621837, 2016). "The TERT promoter is in general unmethylated in normal cells, while its methylation is required for TERT expression and telomerase activation in cancer cells." (PMID 27438857, 2016). "In this review, we will discuss recent progress in understanding the molecular mechanisms of TERT regulation in human and mouse tissues and cells, and during cancer development." (PMID 27367732, 2016). "TERT or telomerase not only provides cancer cells with a proliferation advantage by stabilizing telomere size, but also displays multiple activities independently of telomere-lengthening function." (PMID 27438857, 2016). "Associations between single nucleotide polymorphisms (SNPs) at 5p15 (TERT-CLPTM1L) and multiple cancer types have been reported." (PMID 26621837, 2016). "Human TERT (hTERT) expression increases significantly during tumorigenesis, correlating with the increased proliferative potential of cancer cells." (PMID 27367732, 2016). "It is believed that the CC genotype promotes TERT transcription, thereby upregulating telomerase activity and maintaining telomere length required for unlimited proliferation of cancer cells." (PMID 27561898, 2016). "Even in telomerase positive cancer cells, there are only several hundred TERT proteins in a cell, a challenge for immunotherapy." (PMID 27240403, 2016). "Taken together, the cooperation between GABP or other ETS family transcription factors and the mutant TERT promoter is a novel mechanism for induction of TERT expression and telomerase activation in cancer." (PMID 27438857, 2016). "However, it remains unclear how these TERT variants contribute to cancer susceptibility." (PMID 26934125, 2016). "The catalytic subunit of the telomerase complex is termed Telomerase Reverse Transcriptase (TERT) and its expression has been observed in most malignant cancers including PCa." (PMID 27437772, 2016). "Despite the numerous studies revealing telomerase and TERT expression in the vast majority of human cancer, it remains poorly defined when telomerase is activated in carcinogenesis, especially in an in vivo setting." (PMID 27438857, 2016). "Significantly higher expression of TERT was observed in the NPC tissues compared to that in the non-cancer nasopharyngeal tissues (P < 0.001)." (PMID 26621837, 2016). "TERT directly promotes cancer cell invasion and metastasis by inducing epithelial-mesenchymal transition and other mechanisms." (PMID 27438857, 2016).
cancer (continued). "The role of telomerase reverse transcriptase (TERT) has been extensively investigated in the contexts of aging and cancer." (PMID 27300262, 2016). "Additional studies are clearly warranted to verify the feasibility of using cell-free circulating plasma TERT mRNA to diagnose the carcinoma early and to monitor treatment response in these patients." (PMID 27501725, 2016). "The study also demonstrated a relationship between TERT mutations and germline variants in telomere components (TERC/TERT/RTEL1), which is relevant given interest in telomeres and cancer more generally." (PMID 26244119, 2015). "We have previously reported that introduction of NS into TERT-immortalized fibroblast and cancer cells resulted in the significant increase of the expression of MYC, OCT4 and SOX2." (PMID 25569094, 2015). "TERC is ubiquitously expressed in all normal and cancer cells, whereas TERT, which is involved in cellular immortalization and carcinogenesis, acts as a rate-limiting factor for the activation of telomerase." (PMID 25435972, 2015). "Over 90% of cancers show an up-regulation of the telomerase enzyme, which can occur by TERT over-expression as well as by other means." (PMID 25859550, 2015). "TERT expression is also increased in cancers, and prognostic significance was demonstrated in many cancer types." (PMID 26020272, 2015). "Up-regulation of TERT is a key component of the transformation processes in many malignant cancer cells." (PMID 26158411, 2015). "In summary, our findings regarding genetic variation in the TERT and CLPTM1L region and GIST risk add to the growing body of literature suggesting the importance of this genetic region to cancer development." (PMID 26372813, 2015). "Given the key role of TERT and telomere stabilization in cancer development and progression, it is important to address the effect of DNMTIs on TERT expression and telomere function for their anti-cancer activity." (PMID 25682873, 2015). "Recently, TERT has been shown to be a critical factor in a number of other biological processes, including cell proliferation and cancer metastasis." (PMID 25435972, 2015). "TERT is of great importance for genome integrity and plays a crucial role in cancer initiation and progression." (PMID 26020272, 2015). "The experiments also showed that TERT activity in these cells was similar to that found in cancer cells that can divide indefinitely." (PMID 26194807, 2015). "Analysis of WGS data led to the discovery of recurrent genomic rearrangements involving TERT promoter region, which were associated with very high expression levels of TERT, pointing to a potential mechanism for TERT deregulation that might be found in other cancers." (PMID 25859550, 2015). "The TERT and CLPTM1L gene have been identified to be associated with carcinogenesis of at least 15 distinct cancers." (PMID 26372813, 2015). "Recent studies have suggested polymorphisms in the TERT and CLPTM1L region are associated with carcinogenesis of many distinct cancer types, including gastrointestinal cancers." (PMID 26372813, 2015). "It is interesting that TERT exhibited higher CM in cancer than normal tissue (0.27 vs. 0) but a lower average methylation level (0.53 vs. 0.65)." (PMID 26659027, 2015). "Several cancer susceptibility loci identified in GWAS, such as the 8q24 and TERT-CLPTM1L loci, have also been associated with numerous other cancer sites." (PMID 25789475, 2015). "Activation of TERT transcription occurs in most human cancers where telomerase activity increases to counteract telomere shortening, thereby circumventing the normal limits on cellular proliferation." (PMID 25487306, 2015). "As with ChRCC, TERT mRNA levels vary widely within other cancer types, from undetectable to thousands of units by RNA-seq." (PMID 25859550, 2015). "Obvious candidates for investigation are TERT at 5p15.33 and MYC at 8q24.21, in which SCNA were identified in multiple cancer types matching SNP associations in those genomic regions." (PMID 26575185, 2015).
cancer (continued). "Enzymatic activity of Telomerase Reverse Transcriptase (TERT) is important in maintaining the telomere length and has been implicated in cancer and aging related pathology." (PMID 24423165, 2014). "Multiple factors or pathways contribute to the cancer-specific telomerase activation, but the primary determinant is telomerase reverse transcriptase (TERT), a catalytic subunit of the telomerase enzyme complex." (PMID 24803525, 2014). "In this report, we discovered that endoplasmic reticulum (ER) stress transiently activates the catalytic components of telomerase (TERT) expression in human cancer cell lines and murine primary neural cells." (PMID 24119029, 2014). "Transcription of TERT gene is likely the key determinant in the regulation of telomerase activity; TERT transcriptional activity is specifically up-regulated in cancer cells, but it is silent in most normal cells." (PMID 24572088, 2014). "Higher levels of TERT expression or telomerase activity promote cancer progression and serve as prognostic markers in a number of human malignancies." (PMID 24742867, 2014). "Although MYC has been well studied in the context of TERT regulation in cancer cells, the stability of TERT suppression by MYC inhibition is not well understood." (PMID 24550717, 2014). "In a previous study of other cancers, telomerase activity was shown to depend on the existence of full-length TERT gene expression." (PMID 24758186, 2014). "In this context, telomerase reverse transcriptase (TERT) serves as the catalytic subunit of the telomerase complex and has been shown to contribute to the immortalization of cancer cells." (PMID 24726063, 2014). "Cell cycle inhibitors p16INK4a and p27KIP1 have also been shown to down-regulate TERT expression in cancer cells." (PMID 24572088, 2014). "Previous studies have identified many of the factors which individually contribute to activate or repress TERT levels in cancer cells." (PMID 24550717, 2014). "Because the TERT amplification was previously found in many kinds of cancer, we examined TERT gene copy numbers in 6 MCC cell lines and 14 patient-derived frozen tumors using qPCR." (PMID 25301727, 2014). "All these findings, not only provide insights into telomerase activation in carcinogenesis, but also reveal clinical significance of telomerase/TERT-related assessments in cancer diagnosis and outcome prediction." (PMID 25301727, 2014). "The telomerase signaling pathway and inherited variation in TERT have been found to be associated with the development of EOC and other cancers." (PMID 24774302, 2014). "Multiple transcription factors modulate TERT and previous studies have identified many of those which individually contribute to activate or repress telomerase levels in cancer cells, resulting in a highly complex picture of TERT regulation." (PMID 24550717, 2014). "Activation of TERT is considered a crucial step in tumorigenesis, and therefore it is a potential therapeutic target against cancer." (PMID 24416313, 2014). "Immortalization is one of the key hallmarks of any given malignant tumor, and increased telomerase activity and TERT gene expression are recurrently found in human cancers." (PMID 24803525, 2014). "In the endogenous context, TERT expression clearly is essential in most cancer cells and it is likely that a variety of backup mechanisms exist which are capable of subverting TERT suppression as we previously observed." (PMID 24550717, 2014). "Recently, recurrent point mutations in the telomerase reverse transcriptase (TERT) promoter region have been found in many human cancers, leading to a new transcription factor binding site, increased induction of TERT and subsequently to telomere maintenance." (PMID 24726063, 2014). "More evidences should be provided in future regarding the association between TERT-CLPTM1L genomic region and cancer risk in different races." (PMID 23738012, 2013).
cancer (continued). "It looks that only TERT downregulation starts all the long pathway to induce apoptosis and cancer cell elimination." (PMID 23677713, 2013). "We have reported that MCAF1 is required for cancer cell proliferation by activating the transcription of the telomerase genes, TERT and TERC." (PMID 23935871, 2013). "Previous studies reported that TERT gene and CLPTM1L gene associated to the risk of many type of cancers." (PMID 23738012, 2013). "The up-regulation of TERT expression leads to maintenance of telomeres length, resulting in unlimited proliferation and immortalization of cancer cells, one of the hallmarks of carcinogenesis." (PMID 23752272, 2013). "In many types of cancer, TERT shows a high-level of expression, which possibly induces excessive cell growth and carcinogenesis." (PMID 24171766, 2013). "Remarkably, telomerase (TERT) expression is deregulated in approximately 85% of cancers, through TERT amplification or 5p chromosomal gains." (PMID 23752272, 2013). "TERT-CLPTM1L genomic region have been extensively studies in many cancer sites in different populations, but the results are conflicting." (PMID 23738012, 2013). "For instance, the c-Myc which can activate telomerase complex (telomerase and TERT) is overexpressed in many forms of cancers." (PMID 24369491, 2013). "TERT protein supports the maintenance and expansion of normal and cancer stem cells both by telomerase-dependent and -independent mechanisms." (PMID 23229821, 2013). "Telomerase activity has been detected in ∼85% of cancers, and is a characteristic of most cancers; in several TERT-transgenic mouse models, constitutive telomerase expression increased cancer incidence." (PMID 22363464, 2012). "The sequence variants in the TERT and cleft lip and palate transmembrane 1 like (CLPTM1L) gene regions are associated with susceptibility to many types of cancer." (PMID 22221621, 2012). "Recent reports have shown that the relationship between TERT and Wnt pathway activation is in fact bidirectional, both in embryonic stem (ES) cells and cancer." (PMID 23061047, 2012). "Recently, increasing evidence suggests that telomere maintenance genes, such as TERT, TERC, TERF1, TERF2, TINF2, TERF2IP and POT1 are associated with cancer risk." (PMID 22970196, 2012). "It is mainly present in the nucleus, but about 10–20% of cellular TERT localizes in mitochondria (mt), both in telomerase-expressing normal cells and in cancer cells." (PMID 23061047, 2012). "TERT can increase cancer cell fitness improving mitochondrial activity and resistance to apoptosis (see Section “TERC-independent Reverse Transcriptase Activity” and references therein)." (PMID 23061047, 2012). "It seems that β-catenin regulates TERT expression in ES cells through the binding to the pluripotent transcription factor Klf4, while in human cancer cells, TERT appears as a direct target of β-catenin/TCF4-mediated transcription." (PMID 23061047, 2012). "Studies examining the role of the cellular reverse transcriptase telomerase (TERT) during ageing have been complicated by the cancer-promoting effects of telomerase." (PMID 21115536, 2011). "The vast majority of cancers depend on expression of telomerase, which requires substantial upregulation of TERT expression, for their continued proliferation, strongly implicating TERT as the predominant gene involved in this association." (PMID 21949822, 2011).
cancer (continued). "Current anti-cancer approaches targeting telomerase are varied, ranging from RNA interference of the RNA or TERT component to identification of novel compounds targeting telomerase activity." (PMID 20678253, 2010). "Our study adds to the growing evidence that, as well as the 8q24 locus, the TERT-CLPTM1L locus at 5p15.33, is a general cancer susceptibility locus." (PMID 20628624, 2010). "The NK activity-stimulating effect of rAAV-/rAdv-hTERTC27 represents a novel way to exploit the functions of TERT in cancer treatment." (PMID 20856939, 2010). "Current understanding on the relationships between hypoxia, hypoxia-inducible factor-1 (HIF-1) and telomerase reverse transcriptase (TERT) gene expression are largely based on in vitro studies in human cancer cells." (PMID 16961934, 2006). "RAS mutations are considered weak as they are common in benign thyroid neoplasms and other cancers, whereas RET, NTRK, and ALK rearrangements, along with mutations in BRAF, EIF1AX, and the TERT promoter, are termed strong and are often associated with malignant tumors." (PMID 39744583, 2025). "The TERT oncogene plays several roles in the development and progression of cancer cells." (PMID 40241101, 2025). "While the TERT mutation is not typically considered a primary cancer driver event, it has been associated with poorer prognosis in various cancer types, such as AGCT." (PMID 39592485, 2025). "It is well established that TERT is a potent driver for cancer development and progression." (PMID 40813762, 2025). "Our results suggest that TERT Delta 2–4 enhances cancer cells’ resistance to cell death." (PMID 40000722, 2025). "Variations in TERT expression between benign and malignant melanocytic lesions could have significant clinical relevance, especially in supporting early cancer diagnosis." (PMID 40361989, 2025). "In particular, regarding TC, THER-saturated expression of the lncRNAs MALAT1 and ACVR2B-AS1 enhanced proliferation, migration, and invasion of cancer cells, by acting as microRNA sponges that would upregulate oncogenic targets and pathways, with TERT’s direct involvement still obscured." (PMID 41154428, 2025). "The OncoExTra assay identified both common and rare TERT promoter alterations, which are prognostic for cancer progression, including commonly occurring G-to-A substitutions occurring –124 and –146 bp relative to the TERT transcription start site known to drive increased telomerase expression." (PMID 40711866, 2025). "However, some studies have indicated that, in certain cancer cell types, TERT is predominantly localized to the cytoplasm." (PMID 39871386, 2025). "Some cancers with this TERT enhancement may include ovarian cancer, squamous-cell carcinoma, esophageal cancer, adrenocortical carcinoma, and lung adenocarcinoma." (PMID 39858038, 2025). "Thus, marked alterations in mitochondrial function and TERT upregulation are critical for enabling the metabolic flexibility that sustains cancer cell growth and survival." (PMID 39940762, 2025). "Implications of our data are that additional TERT isoforms may code for novel proteins and that better cancer drug efficiency could be achieved by targeting TERT Delta 2–4." (PMID 40000722, 2025). "Several new anti-cancer drugs were developed to target TERT." (PMID 40332222, 2025). "The catalytic subunit TERT is expressed in most cancers and proliferating cells." (PMID 41321994, 2025). "Pan-cancer evidence linking TERT-promoter hypermethylation with malignancy." (PMID 41375001, 2025). "TERT overexpressionin many cancers helps cells evade normal proliferative limits." (PMID 40384113, 2025). "TERT stands out due to its well-documented function in telomere maintenance and cancer development." (PMID 40278994, 2025). "Notably, several cancer-associated genes are located within a 1 Mb proximity including CLPTM1L, TERT, BRD9, TRIP13, NKD2, LPCAT1, and IRX4." (PMID 40278994, 2025).